HGF (hepatocyte growth factor)
Diseases named in the same sentence as HGF in open-access papers (continued):
Sharing a sentence is not in itself a finding about the gene and the disease.
myocardial infarction (continued). "Our findings are in accordance with previous studies, which have shown favorable effects of HGF in different experimental models of cardiovascular diseases, such as myocardial infarction and autoimmune myocarditis." (PMID 22815907, 2012). "After myocardial infarction and compared to ischemia-reperfusion injury, there was a significantly lower accumulation of c-Kit+ cells in the heart, consistent with the lower expression of endogenous IGF-1 and HGF in the myocardial infarction group." (PMID 22590612, 2012). "The present results demonstrate that intra-myocardial injection of HGF and IGF-1 in a rat model of healed myocardial infarction caused a significant decline in arrhythmias of conscious freely moving animals subjected to stressful conditions." (PMID 21445273, 2011). "In the heart, acute myocardial infarction, ischemia reperfusion injury, and congestive heart failure induce expression of HGF." (PMID 21541335, 2011). "In the HGF group, myocardial infarct and peri-infarct zone had higher HGF expression compared with the normal zone." (PMID 23554631, 2010). "There was higher HGF expression in the myocardial infarct and peri-infarct zones of the treatment group than that in the control groups (P < 0.01)." (PMID 23554631, 2010). "Notably, transgenic HGF overexpression improves post-myocardial infarction recovery in murine models by enhancing angiogenesis, reducing cardiomyocyte apoptosis, and restoring ventricular contractile function." (PMID 41000109, 2025). "HGF-eMSC primed BM-MSCs demonstrate improved vasculogenic potential and cell viability, which ultimately enhance vascular regeneration and improve cardiac function after myocardial infarction." (PMID 37373454, 2023). "Furthermore, previous studies have demonstrated the therapeutic effects of HGF on myocardial infarction in vivo." (PMID 33072729, 2020). "An HGF plasmid has also been delivered with US + MBs in a rat model of myocardial infarction." (PMID 31238531, 2019). "Some researchers have shown that miR-26a could inhibit the activity of angiogenesis in liver cancer, acute myocardial infarction, and diabetes by directly targeting signaling pathways, such as hepatocyte growth factor-cMet pathway and BMP/Smad1 pathway." (PMID 31730486, 2019). "In addition, numerous preclinical studies have recently examined the use of HGF as a pro-angiogenic and cardio-protective agent in the treatment of myocardial infarction, heart failure, and limb ischemia." (PMID 30594174, 2018). "Circulating HGF increased in the early stage of acute myocardial infarction." (PMID 25890008, 2015). "Myocardial HGF/c-Met is upregulated in the heart following myocardial infarction." (PMID 24705272, 2014). "Besides the liver, serum HGF elevation occurs during the early phases of both acute myocardial infarction (AMI) and heart failure (HF)." (PMID 24642599, 2014). "By promoting angiogenesis and inhibiting apoptosis, endogenous HGF may play an important role in cardioprotection as well as in the regeneration of endothelial cells and cardiomyocytes after myocardial infarction." (PMID 24983946, 2014). "Our previous studies have shown that over-expression of HGF not only could induce active angiogenesis, but reduce cardiomyocyte apoptosis and proliferation in the myocardial infarct and peri-infarct zones." (PMID 23301013, 2013). "In animal models of myocardial infarction, the intramyocardial injection of hepatocyte growth factor (HGF) and insulin-like growth factor 1 (IGF-1) activated the formation of cardiomyocytes and coronary vessels within the infarcted area through their binding to the receptors of the resident CSCs." (PMID 23407679, 2013). "The myocardial infarct and peri-infarct zones had higher HGF expression compared with the normal zone, and the normal zone was the lowest among the three myocardial zones in the HGF group." (PMID 23301013, 2013).
myocardial infarction (continued). "Systemic administration of hepatocyte growth factor (HGF), a multifunctional cytokine involved in tissue repair, induces myocardial angiogenesis which contributes to the improvement in cardiac performance of mice after myocardial infarction." (PMID 17686146, 2007). "Thus, therapeutic applications of HGF have been tested in various diseases including liver cirrhosis, chronic renal failure, lung fibrosis, myocardial infarction, arteriosclerosis obliterans, amyotrophic lateral sclerosis (ALS, Lou Gehrig's disease), and acute spinal cord injury." (PMID 37985931, 2024). "Therefore, two days after coronary artery reperfusion could be a perfect moment for the administration of microencapsulated HGF to prevent secondary reactions of myocardial infarction." (PMID 36826582, 2023). "The delivery of hepatocyte growth factor genes using mesoporous organosilica nanoparticles also demonstrated enhanced paracrine activity in hepatocyte growth factor-transfected myocardial stem cells, resulting in reduced apoptosis and increased angiogenesis in a rat model of myocardial infarction." (PMID 33291312, 2020). "To test this hypothesis, we injected superparamagnetic iron oxide (SPIO) and luciferase double-labelled BMSCs transfected with lentivector-mediated human HGF into the border of the infarct zone 7 days after myocardial infarction under echocardiography guidance." (PMID 27804974, 2016). "With HGF mimetics currently in phase II clinical trials for treating myocardial infarction and kidney dysfunction, our results suggest that these drugs might also be used to control chronic inflammation in muscular dystrophy and other inflammatory myopathies without compromising host immunity." (PMID 25906153, 2015). "Further, VEGF-A, IGF-1, HGF, and IL-8 gene expression was promoted at a high level by CXCL-6 in a myocardial infarction model." (PMID 37635970, 2023). "Investigations of TIMP-1 have shown attenuated maladaptive cardiac remodeling at the site of myocardial infarction, inhibition of cardiomyocyte apoptosis, and enhanced pro-vasculogenic factor release from cardiac fibroblasts, including VEGF, FGF, and HGF." (PMID 34639108, 2021). "Hepatocyte growth factor (HGF) and vascular endothelial growth factor (VEGF), which are protective against general tissue damage, are suggested to promote tissue repair in acute myocardial infarction and liver damage models treated with Muse cells." (PMID 33924240, 2021). "Combined delivery of HGF and VEGF to infarcted myocardium showed an increase of left ventricle (LV) wall thickness and capillary density, reduce myocardial infarction size and improve dilatation index." (PMID 33072729, 2020). "VEGF, bFGF, HGF and IGF‐1 contents in the CSps group were 3.06, 8.75, 1.61 and 2.54 times those in the Control group, respectively (P < 0.05) at 1 week after myocardial infarction." (PMID 29736937, 2018). "At 4 weeks after myocardial infarction, VEGF, bFGF, HGF and IGF‐1 contents in the CSps group were 1.96, 3.12, 2.01 and 3.66 times those in the Control group, respectively (P < 0.05)." (PMID 29736937, 2018). "We studied whether the in situ activation of eCSCs by insulin-like growth factor 1 (IGF-1) and hepatocyte growth factor (HGF) could be increased using a newly developed hydrogel in chronic myocardial infarction (MI)." (PMID 24395494, 2014). "CSCs and the intramyocardial injection of HGF and IGF-1 resulted in the regeneration of the infarcted area and newly formed myocardial tissue at 20 days after the induction of myocardial infarction in rat hearts." (PMID 23407679, 2013). "Adult female rats were examined during pregnancy, after myocardial infarction and ischemia-reperfusion injury with/out insulin like growth factor-1(IGF-1) and hepatocyte growth factor (HGF)." (PMID 22590612, 2012).
myocardial infarction (continued). "In this study, a bioactive, protease-degradable polyethylene glycol (PEG)-based hydrogel was used to deliver hepatocyte growth factor (HGF) and VEGF following acute myocardial infarction." (PMID 23226440, 2012). "In this study we tested the hypothesis that mobilization of CPCs through locally delivered Hepatocyte Growth Factor and Insulin-Like Growth Factor-1 to heal chronic myocardial infarction (MI), lowers the proneness to arrhythmias." (PMID 21445273, 2011). "Because HGF and myoblast sheet therapy are antifibrotic after acute myocardial infarction, we tested whether L6-HGF sheets could reverse or reduce myocardial fibrosis once it already develops, as in the model of MI-induced chronic heart failure." (PMID 21541335, 2011). "HGF preserves cardiac function, attenuates fibrosis and infarct size, promotes angiogenesis and cardiomyocyte survival, and stimulates PI3-kinase/Akt pathway in mice with myocardial infarction." (PMID 40041176, 2025). "Some studies have shown a positive correlation between the serum value of HGF and CRP in patients with other acute or chronic conditions, e.g., chronic liver disease and chronic renal failure requiring renal replacement, or after acute myocardial infarction." (PMID 39457546, 2024). "After myocardial infarction, CD117+ MPCs migrate to the area bordering the infarction through the activation of HGF-c-met, SDF1-CXCR4, and IGF1-IGFR signaling mechanisms, thus providing protection and repair of damaged myocardium presumably by secretion of bioactive compounds." (PMID 37958542, 2023). "As hepatocyte growth factor (HGF) is present in the circulation after endothelial injury, its higher levels correlate with multiple cardio-cerebrovascular diseases, including atherosclerosis, diabetes mellitus, and acute myocardial infarction." (PMID 34421795, 2021). "These in vitro data was the basis to pre-clinical test of the intracoronary injection of small amounts of IGF-1 and HGF (a single dose ranging from 0.5 to 2 μg HGF and 2 to 8 μg IGF-1) to pigs subjected to acute myocardial infarction (AMI) by transient coronary occlusion." (PMID 31275242, 2019). "Direct assessment of the content of growth factors showed that VEGF, bFGF, HGF and IGF‐1 in pericardial effusion from the CSps group were many fold higher than those from the Control group at both early and late time points after myocardial infarction." (PMID 29736937, 2018). "Finally, direct IGF-1 + HGF administration was recently evaluated in a porcine model of chronic myocardial infarction (MI), in which growth factor delivery reduced pathological hypertrophy, led to formation of new small cardiomyocytes, and increased capillarization." (PMID 27423905, 2016). "In the myocardial infarction group there was a divergent reactivity, with marginal up-regulation of IGF-1 (P = 0.06), especially at the site of injury and significant (P<0.05) down-regulation of endogenous HGF." (PMID 22590612, 2012). "In vivo, HGF gene-modified BMSCs significantly accelerated the myocardial tissue repair of myocardial infarction after trauma compared with un-transfected BMSCs, while BMSCs with HGF gene knocked out could not improve blood vessel regeneration in the limb ischemia model." (PMID 29510550, 2018). "In the present study, we tested the hypothesis that activating the lineage commitment and progeny formation of resident CPCs, via the HGF/IGF-1-receptor systems, can also ameliorate the electrical competence of the infarcted heart, in a rat model of chronic myocardial infarction (MI)." (PMID 21445273, 2011).
liver cancer (69 papers, 2004 to 2025). An epithelial or non-epithelial malignant neoplasm that arises from the liver. "Our analysis demonstrated that the HGF/MET pathway was associated with liver cancer cell proliferation and that Met expression was involved in regulation of the compound transcription factor, AP1 (comprising cJun, cFos, and ATF)." (PMID 36387747, 2022). "c-MET and its ligand, HGF, are frequently overexpressed in liver cancer and in associated metastases." (PMID 32174795, 2020). "In addition, the development and progression of liver cancer and liver metastases is a multifactorial process, linked to alterations in some prominent cellular signaling pathways, including dysregulation of HGF, EGF, and IGF-1." (PMID 34572344, 2021). "Conditional depletion of HGF in CAFs resulted in decreased development of liver cancer, and depletion of the HGF receptor MET in hepatocytes or tumour compartments reduced tumour growth." (PMID 39780187, 2025). "HSCs participate in liver regeneration but exhibit inhibitory effects on liver cancer by secreting cytokines such as hepatocyte growth factor (HGF) and IL-6." (PMID 40918452, 2025). "Inhibition of FUT8 can weaken hepatocyte epidermal growth factor (EGF) and hepatocyte growth factor (HGF), and thus reduce the incidence of liver cancer." (PMID 35410157, 2022). "C7 peptide can prevent metastasis and invasion in liver cancer by inhibiting the Akt and Erk1/2 signaling pathway, blocking the combination of HGF and c-Met, and inhibiting HGF/c-Met and its downstream signaling pathway." (PMID 36278230, 2022). "Liver cancer cell-derived exosomes are able to induce Sorafenib resistance in vivo and in vitro by suppressing apoptosis through the regulation of the HGF/c-Met/Akt pathway." (PMID 36078082, 2022). "It is known that HGF facilitates metabolic reprogramming by regulating the Warburg effect and glutaminolysis in liver cancer cells." (PMID 33718248, 2021). "Hepatocyte growth factor (HGF) is an HSC-derived paracrine factor regulating liver cancer cell proliferation via its receptor c-Met and downstream MAPK and Akt pathways." (PMID 33558482, 2021). "In a study performed in different liver cancer cell lines, activated hepatic stellate cells promoted residual tumor progression by modulation of autophagic survival to proliferation via HGF/c-Met signaling." (PMID 34572344, 2021). "HGF can induce reactive oxygen species (ROS) signaling, thus increasing cell adhesion, migration, and invasion of liver cancer." (PMID 34572344, 2021). "The HGF-MET axis was reported to inhibit pyruvate dehydrogenase complex (PDHC) activity but activate GLS to facilitate glutaminolysis in multiple liver cancer cells." (PMID 33016874, 2020). "In general, the mechanism of the HGF/c-Met pathway involvement in liver cancer requires more research, and c-Met inhibitors are a potential and promising therapeutic strategy in patients with HCC." (PMID 32117981, 2020). "Actually, in HGF-stimulated liver cancer cells, we found that Arf6-KD inhibited Rac1 activation and further over-expression of Arf6(Q67L) partially restored such inhibition." (PMID 31752956, 2019). "HCC cells delivered exosomes to the sorafenib sensitive of liver cancer cells, which activated the HGF/c-Met/Akt signaling and inhibited sorafenib-induced apoptosis of host cells, thereby enhancing sorafenib resistance in liver cancer cells." (PMID 30616541, 2019). "A risk scoring system was developed with six covariates: etiology, platelet count, Barcelona Clinic Liver Cancer stage, protein induced by vitamin K absence-II, HGF, and FGF." (PMID 29558905, 2018).
liver cancer (continued). "We conducted a study of plasma hepatocyte growth factor (HGF) in a clinical trial of proton radiotherapy in patients with unresectable liver cancers (NCT00976898), and in an observational study for liver cancer patients undergoing surgical treatments." (PMID 30374460, 2018). "In liver cancer, overexpression of HGF promotes carcinogenesis through an HGF-autocrine mechanism, resulting in high levels of neovascularization mediated by dynamic interaction between the endothelial and tumor cells." (PMID 30208970, 2018). "In this prospective study, we found a significant association between elevated plasma HGF levels and worsening of CTP score occurring in liver cancer patients treated with high-dose radiotherapy." (PMID 30374460, 2018). "Another molecular mechanism involved in HCC cell-derived EV-induced sorafenib resistance includes the activation of the hepatocyte growth factor (HGF)/c-Met/Akt signaling pathway in liver cancer cells." (PMID 30369925, 2018). "We found that HCC cell-derived exosomes enhanced sorafenib resistance in liver cancer in vitro by inhibiting sorafenib-induced apoptosis via activation of the HGF/c-Met/Akt signaling pathways." (PMID 27716356, 2016). "Taken together, our study suggests that GPC3 is involved in HCC cell migration and motility through HS chain-mediated cooperation with the HGF/Met pathway, showing how HS targeting has potential therapeutic implications for liver cancer." (PMID 26332121, 2015). "Altogether, these observations suggest that the HS chains on GPC3 are involved in HGF/Met activation in liver cancer cells." (PMID 26332121, 2015). "In general, the HGF expression levels in the liver cancer microenvironment after surgery show marked increases, implicating HGF as one of the main causes of HCC recurrence and metastasis." (PMID 26099202, 2015). "This suggests that IL-18 can be used as an index of the co-presence of type 2 diabetes and liver cancer whereas HGF is specific only for the cancer." (PMID 26226632, 2015). "BALB/c nude mice were inoculated with MHCC97H cells or with tumor fragments of 10 patient-derived primary liver cancer explants selected according to c-Met/HGF expression levels." (PMID 25256830, 2014). "Mean circulating levels of HGF in benign and malignant liver tumors were within the reference range." (PMID 14960204, 2004). "The amount of circulating HGF was significantly higher in patients with malignant liver tumors than in patients with benign lesions." (PMID 14960204, 2004). "In liver cancer, iCAFs showed high expression of HGF, promoting tumour growth via the HGF-MET axis." (PMID 39780187, 2025). "In liver cancer, overexpression of the HGF/c‐Met pathway leads to excessive HGF secretion by mesenchymal cells, synergising with pathways such as PI3K/Akt/mTOR, MAPK/ERK, and Rho GTPases to promote tumour proliferation, remodel the cytoskeleton, and facilitate metastasis." (PMID 40525649, 2025). "In addition, other studies have shown that the HGF-Met axis plays an important role in chemotherapy resistance by coordinating liver cancer metabolism and autophagy." (PMID 36505831, 2022). "Here, we have found the hepatocyte growth factor (HGF) receptor (MET) is required for mTOR activation-stimulated mitochondrial oxidative phosphorylation (OXPHOS) in a phosphorylation-dependent manner in liver cancer." (PMID 33377662, 2020). "Targeting HCC cell-derived exosomes or the HGF/c-Met/Akt pathway may help improve treatment efficacy in liver cancer." (PMID 27716356, 2016). "In this study, we found that treatment of HCC cells with MHCC-97 L and MHCC-97H cell-derived exosomes increased HGF levels in the medium, which further activated p-Met in liver cancer cells, ultimately leading to activation of its key downstream protein, p-Akt." (PMID 27716356, 2016). "Moreover, nobiletin was reported to inhibit phosphorylation of AKT and phosphorylation of ERK2 in HGF-treated liver cancer HepG2 cells." (PMID 26689156, 2015).